PCSK9 (proprotein convertase subtilisin/kexin type 9)
Diseases named in the same sentence as PCSK9 in open-access papers (continued):
Sharing a sentence is not in itself a finding about the gene and the disease.
unstable angina (17 papers, 2019 to 2026). "Hence, the combination of PT and PCSK9 increases the incidence of cardiovascular incidents in patients with angina-like chest pain, which is beneficial for risk evaluation." (PMID 35566668, 2022). "When evaluating the association of PCSK9 levels to different routine coagulation indexes in patients with angina pectoris, high PCSK9 levels correlated with low prothrombin time, and this combination predicted a poor cardiovascular outcome." (PMID 35323669, 2022). "Moreover, PCSK9 inhibitors such as alirocumab and evolocumab promote LDL-C clearance by blocking PCSK9 function, thereby ameliorating CVDs such as AS and angina." (PMID 41345744, 2025). "The result demonstrated that patients used PCSK9 inhibitors could reduce angina than those who used statins or placebo treatment." (PMID 39259104, 2024). "More importantly, elevated NFS and PCSK9 could better predict adverse cardiovascular events in patients with angina-like chest pain, indicating that NFS might improve the ability of PCSK9 to predict outcomes." (PMID 34996457, 2022). "Hence, the combination of PCSK9 and PT (or PT-t) had an additive impact on the incidence of cardiovascular events in patients with angina-like chest pain, which was benefited for cardiovascular risk stratification." (PMID 34809656, 2021). "In the current study, we, for the first time, found that PCSK9 was only independently correlated with lower PT levels in patients with angina-like chest pain who took no lipid-lowering therapy." (PMID 34809656, 2021).
atrial fibrillation (16 papers, 2018 to 2025). A disorder characterized by an electrocardiographic finding of a supraventricular arrhythmia characterized by the replacement of consistent P waves by rapid oscillations or fibrillatory waves that vary in size, shape and timing and are accompanied by an irregular ventricular response. "Additionally, high PCSK9 levels were found to be associated with a ROS-mediated pathway in patients with atrial fibrillation." (PMID 41226572, 2025). "Recently, high circulating levels of PCSK9 were found to be associated with increased downstream signaling activation, a mechanism that seems to be related to an ROS-mediated pathway, in patients with atrial fibrillation (AF)." (PMID 35326219, 2022). "Similarly, atrial fibrillation patients show a strong correlation between PCSK9 plasma levels and platelet reactivity as elevated PCSK9 levels positively correlate with elevated risk for this cardiovascular event." (PMID 33834043, 2021). "Current studies demonstrate that gene modulation of dyslipidemia-associated targets (in particular, PCSK9) can have a positive effect not only on the atherosclerotic process but also on the risk of atrial fibrillation (AF)." (PMID 40725196, 2025). "Subsequently, a direct correlation between urinary excretion of 11-dehydro-thromboxane-B2, a marker of in vivo platelet activation, and circulating PCSK9 levels was reported in patients with atrial fibrillation." (PMID 35596184, 2022). "Similarly, platelets incubated with PCSK9, at the concentration found in the circulation of 1 patients with atrial fibrillation (AF), increased platelet aggregation and the release of thromboxane B2 (TxB2), which is a marker of in vivo platelet activation." (PMID 40357205, 2025). "Similarly, platelets incubated with PCSK9, at the concentration found in the circulation of atrial fibrillation (AF) patients, increased platelet aggregation and platelet thromboxane B2 (TxB2) release, a marker of in vivo platelet activation." (PMID 35326219, 2022). "In subjects with atrial fibrillation (AF), PCSK9 may promote platelet activation and inhibit the clearance of FVIII, which could result in the increase of risk of arterial thrombosis complications." (PMID 35323699, 2022). "On the other hand, PCSK9 levels were also related to the cardiovascular event rate and urinary excretion of 11-dehydro-thromboxane (Tx) B2, a marker of platelet cyclooxygenase (COX)-1 activity and an indirect marker of platelet activation, in patients with atrial fibrillation." (PMID 35323669, 2022).
Cognitive impairment (16 papers, 2019 to 2026). Abnormal cognition is characterized by deficits in thinking, reasoning, or remembering. "For example, in a drug-targeted MR analysis, the authors found a causal association between genetic variants in PCSK9 inhibitors and statins and the risk of cognitive impairment." (PMID 39172202, 2024). "In rodents fed a high-fat diet, hippocampal neuronal apoptosis is associated with an increase in PCSK9 expression, while the PCSK9 inhibitor alirocumab reduces neuroinflammation and ameliorates cognitive deficits." (PMID 35404972, 2022). "On the other hand, the cholesterol depletion hypothesis is in full accordance with the results of in vivo animal studies, in which silencing of lipoprotein receptors, implicated in cholesterol uptake and target of PCSK9, led to cognitive impairment, which was likely related to neuronal loss." (PMID 36293049, 2022). "The results indicate that T2DM rats displayed cognitive deficits, while PCSK9 inhibitor treatment appeared to ameliorate the impaired spatial learning and memory capabilities in T2DM rats." (PMID 39157774, 2024). "Since age and gender have been introduced as the most prominent variables in assessing cognitive impairment, we need compelling data to support any age- and gender-tailored recommendation for PCSK9 inhibitors." (PMID 36506552, 2022). "Additionally, TEM observations indicated that PCSK9 inhibitor treatment protected against cognitive impairment in T2DM rats by reducing neuronal damage." (PMID 39157774, 2024). "The use of PCSK9 inhibitors, similar to statins in cognitive function, did not demonstrate an increased risk of cognitive impairment." (PMID 39767636, 2024). "This study did not fully support the causal relationship between PCSK9 inhibitors and cognitive impairment, which was in consistent with recent studies." (PMID 36506552, 2022). "The impact of PCSK9 on neurocognitive performances in pre-clinical models has been indirectly suggested by the observation that deletion of the LRP1, which is sensitive to the degrading action of PCSK9, leads to a reduced Aβ clearance and to cognitive deficits in mice." (PMID 31178716, 2019).
Hyperglycemia (16 papers, 2019 to 2025). An increased concentration of glucose in the blood. "There was a raised reporting of hyperglycaemias associated with PCSK9 inhibitors treatment compared to the full database (n = 1841/87,274 (2.1%); adjusted-reporting odds ratio (ROR) = 1.14 (1.07–1.22)." (PMID 36383291, 2022). "In general, patients with cancer often show hyperglycemia due to various reasons, and the elevated PCSK9 expression increases the serum LDL levels, which can promote metastatic progression." (PMID 34504788, 2021). "Here, on the basis of our data, we can speculate that in this positive association, a role could be played by hyperglycemia’s effects on VSMC synthetic activity and ability to release PCSK9." (PMID 39940773, 2025). "In this way, PCSK9−/− male mice were with hypoinsulinemia, hyperglycemia and glucose intolerance." (PMID 37435056, 2023). "ANP reduced insulin-induced PCSK9, especially in the context of a medium simulating hyperglycemia." (PMID 30634533, 2019). "Although the anti-PCSK9 vaccine could protect the vaccinated rats against STZ-induced hyperglycemia and improved glucose hemostasis to the same extent as the control rats, the loss of body weight gain in the VS group was evident in a similar fashion to the DC group." (PMID 34504898, 2021). "Meanwhile, this study also emphasized that, PCSK9-mAbs therapy was related to increased report of mild hyperglycemia, but not NOD." (PMID 37435056, 2023). "Interestingly, diabetic patients given PCSK9 inhibitors experienced hyperglycaemia more frequently than non-diabetic patients, namely, 11.3% vs 2.1% in the case of evolocumab and 9.9% vs 1.3% in the case of alirocumab." (PMID 36383291, 2022).
rheumatoid arthritis (14 papers, 2020 to 2026). A chronic, systemic autoimmune disorder characterized by inflammation in the synovial membranes and articular surfaces. "Here, we investigate the role of PCSK9 in relation to the inflammatory activity in patients with rheumatoid arthritis (RA)." (PMID 33461620, 2021). "Our results are supported in part by previous reports on inflammation: PCSK9 levels were decreased in the saliva and serum of chronic periodontitis and rheumatoid arthritis (RA) patients, respectively, compared to healthy controls." (PMID 33255937, 2020). "PCSK9 might also play a role in other autoimmune diseases, such as rheumatoid arthritis (RA)." (PMID 39736777, 2024). "What is also worth mentioning here are the interesting results of the links between PCSK9 levels and inflammatory markers in rheumatoid arthritis (RA)." (PMID 32225075, 2020). "Moreover, another study reports that lower PCSK9 at baseline and at 12 months after TNF inhibitor therapy is related to better response in rheumatoid arthritis (RA) patients." (PMID 37249282, 2023). "Recent research indicates that proprotein convertase subtilisin kexin 9 (PCSK9) inhibitors not only effectively lower LDL-C levels in CKD patients but also exhibit therapeutic potential for autoimmune diseases such as systemic lupus erythematosus, rheumatoid arthritis, and ulcerative colitis." (PMID 38510702, 2024).
autoimmune disease (13 papers, 2019 to 2025). A disorder resulting from loss of function or tissue destruction of an organ or multiple organs, arising from humoral or cellular immune responses of the individual to their own tissue constituents. "Further studies are needed to confirm the association between the inhibition of PCSK9 and the risk of autoimmune diseases." (PMID 37580807, 2023). "A Mendelian randomization study showed that the immunomodulatory effects of PCSK9 could have an effect on autoimmune diseases, and that PCSK9 inhibitors significantly reduced the risk of SLE but increased the risk of asthma and Crohn’s disease." (PMID 38155961, 2023). "We collected single nucleotide polymorphisms (SNPs) of PCSK9 from published genome-wide association studies statistics and conducted drug target MR analysis to detect the causal relationship between PCSK9 inhibitor and the risk of autoimmune diseases." (PMID 37580807, 2023). "There is evidence to suggest that patients suffering from autoimmune diseases exhibit changes in their serum PCSK9 levels, which also have a role in disease development." (PMID 41271978, 2025). "Current research indicates that PCSK9 is a key regulatory factor in the inflammation of chronic and autoimmune diseases." (PMID 38341813, 2024). "Recently, PCSK9’s role in inflammation and immunity, especially its contribution to the pathogenesis of autoimmune diseases, has attracted considerable interest." (PMID 38510702, 2024). "As a result, the inhibition of PCSK9 can alleviate inflammation pathways, leading to a decreased risk of SLE—an autoimmune disease characterized by inflammation affecting various organs." (PMID 37964871, 2023). "Recently, the role of PCSK9 in inflammation and immunity, especially in the pathogenesis of autoimmune diseases, has received increasing attention." (PMID 37580807, 2023). "To date, increased PCSK9 levels and its impact on dyslipidema has been reported in the most common autoimmune disease in childhood, T1DM, and future studies in pediatric Hashimoto thyroiditis are warranted." (PMID 31920978, 2019). "In addition, PCSK9 was found to upregulate the number of Th1 and Th17 cells and promote differentiation in patients with autoimmune diseases." (PMID 39736777, 2024). "In the future, targeting PCSK9 might be a promising strategy for exploring the modulatory function of PCSK9 in the T-cell response and in some abnormal immune activities, such as autoimmune diseases or GVHD posttransplantation." (PMID 39736777, 2024). "Additionally, PCSK9 inhibitors have shown therapeutic effects in the autoimmune disease systemic lupus erythematosus." (PMID 39034950, 2024). "Therefore, we used drug target Mendelian randomization (MR) analysis to investigate the effect of PCSK9 inhibitor on different autoimmune diseases." (PMID 37580807, 2023). "The clinical role of PCSK9 in autoimmune diseases has previously been reported." (PMID 37249282, 2023). "However, the impact of PCSK9 on autoimmune diseases is controversial." (PMID 37580807, 2023). "Although the protective effects of PCSK9 inhibitors (PCSK9i) in cardiovascular diseases (CVD) have been widely established, the impact of PCSK9 on autoimmune diseases remains uncertain." (PMID 37580807, 2023). "Patients with any autoimmune disease who do not exhibit fibrosis showed significantly higher levels of PCSK9 compared to controls." (PMID 41271978, 2025). "Patients with any autoimmune disease and without fibrosis had higher PCSK9 levels than the control group (p < 0.001)." (PMID 41271978, 2025). "However, the therapeutic role of PCSK9 inhibitors in PSC, also an autoimmune disease, has yet to be explored." (PMID 39034950, 2024). "Overall, PCSK9 is not only involved in infectious disease processes but is also closely related to noninfectious inflammation, including lipid metabolism and autoimmune diseases." (PMID 39736777, 2024). "Currently, there is no direct evidence to support the role PCSK9 plays in autoimmune diseases." (PMID 37580807, 2023).
hemorrhagic stroke (13 papers, 2012 to 2026). A stroke caused by a bleed on the brain. "And PCSK9 inhibitors are even the preferred lipid-lowering medications for high-risk patients with hemorrhagic stroke (including patients with a history of hemorrhagic stroke)." (PMID 41601579, 2026). "PCSK9 plays an important physiological role in metabolism, and low lipid levels are considered a risk factor for hemorrhagic stroke, therefore, the safety of PCSK9 inhibitors was previously controversial." (PMID 37200976, 2023). "The point estimate for the GS association with hemorrhagic stroke, OR 1.29 (95% CI 0.76, 2.19), was discordant to the estimate from PCSK9 inhibitor trials (OR 0.96 95% CI 0.75; 1.23), although the confidence intervals overlapped." (PMID 31664920, 2019). "Ezetimibe plus statins was the most likely regimen to cause hemorrhagic stroke compared to placebo (RR: 2.87, 95% CrI: 0.64-15.33; SUCRA: 0.82), followed by statins alone (RR: 1.57, 95% CrI: 1.13-2.21; SUCRA: 0.57) and PCSK9 inhibitors plus statins (RR: 1.56, 95% CrI: 0.69-3.56; SUCRA: 0.53)." (PMID 37881090, 2024). "Another systematic review showed that statins increased the risk of hemorrhagic stroke (RR: 1.15, 95% CI: 1.00-1.32), but PCSK9 inhibitors did not increase the risk (RR: 0.93, 95% CI: 0.58-1.51)." (PMID 37881090, 2024). "Our findings suggest that a different effect on ischemic and hemorrhagic stroke subtypes may be eventually identified for PCSK9 inhibitors." (PMID 31664920, 2019). "A meta-analysis of 23 studies found that low LDL-C levels were associated with hemorrhagic stroke but theorized it may be due to patients’ poor health status in general rather than a causative role PCSK9 or low LDL-C." (PMID 32595449, 2020). "Recently, PCSK9 inhibitor phase III studies, e.g., FOURIER and ODYSSEY randomized trials, reported no significant increase in hemorrhagic stroke among the study population despite profound LDL-C reduction." (PMID 35159988, 2022).
lipid metabolism disorders (13 papers, 2016 to 2026). "PCSK9 inhibitors provide a new possibility for the treatment of lipid metabolism disorders in kidney transplant patients, demonstrating safety and efficacy even in complex situations." (PMID 41478627, 2025). "All the presented data allow us to recognize that PCSK9 plays an important role in experimental CRF-related lipid metabolism disorders." (PMID 26481479, 2016). "PCSK9 inhibitors may be considered a pharmacologic option for treating lipid metabolism disorder and reducing low-density lipoprotein cholesterol in transplant recipients." (PMID 41478627, 2025). "Additionally, dysbiosis of the gut microbiota may lead to abnormal increases in PCSK9 levels, exacerbating lipid metabolic disorders and the occurrence of related diseases." (PMID 41478627, 2025). "The small-molecule peptides in the earthworm protein hydrolysate alleviated lipid metabolism disorders in steatotic hepatocytes by regulating the expression levels of crucial proteins (APOC3, HMGCR, PCSK9, PPAR-Y, SREBP1, C/EBP-a, NPC1L1, CYP7A1)." (PMID 40647090, 2025). "Given the effectiveness of PCSK9-targeted inhibitors in the treatment of CHD and lipid metabolism disorders, it is essential to explore the development of drugs targeting FES." (PMID 38689297, 2024).